CD4 (CD4 molecule)
Diseases named in the same sentence as CD4 in open-access papers (continued):
Sharing a sentence is not in itself a finding about the gene and the disease.
infection (continued). "In acute phase infection, host resistance mainly involves NK cells and CD4+ T cells, and the major IFN-γ producing cells that control parasites in chronically infected mice are CD8+ T cells and to a lesser extent, CD4+ T cells." (PMID 30894865, 2019). "Like the intestine, both VEH/SIV and THC/SIV rhesus macaques showed significant depletion of total CD4+ T cells (absolute counts) in peripheral blood at 14 days post-infection that continued to remain low until 180 days post infection." (PMID 31114576, 2019). "CD4+ T cells were markedly depleted in the intestines at 14 days post-infection and the depletion persisted through 180 days post-infection in both groups." (PMID 31114576, 2019). "Here represents the first instance where endogenous, Salmonella-specific CD4 T cells have been observed to migrate into the gallbladder in response to increased local infection." (PMID 31575775, 2019). "Expression of both fluorophores was detected following infection of the Jurkat T‐cell line while only low levels of the latent reporter were observed following infection of primary CD4+ T cells." (PMID 31855322, 2019). "Taken together, these studies show that, as in other organs, lung and airway Trms, both CD4 and CD8, form an important part of the immune response to a wide variety of pathogenic infections." (PMID 31130965, 2019). "Similar results were observed for the frequencies of CCR7+ DC subsets with the tendency of even more CCR7+CD4+ DCs upon infection with the PSM expressing WT strain." (PMID 31134074, 2019). "Tr1 cells are an important immunoregulatory CD4+ T cell subset that not only prevent immune pathology during Plasmodium infection but can also promote establishment of infection by suppressing Th1 cell-mediated anti-parasitic immunity." (PMID 30809232, 2019). "We performed a real time PCR on the antigen specific CD4 T cells and found that (a) among the miRNAs tested, miRNA146a was significantly up regulated at week 7 post-infection (p.i.) a time point at which increased BLIMP-1 expression peaks in these cells." (PMID 31119107, 2019). "This allowed us to focus on the levels of p24 measured in the APC-T-cell co-cultures resulting from trans infection of CD4+ T cells." (PMID 31304185, 2019). "Given the importance of CM CD4 T cells as primary targets for infection and as key players in the generation and maintenance of adaptive immune responses, these differences likely have implications for the long-term pathogenesis of HIV infection." (PMID 31490965, 2019). "vaccination, memory CD4 T cells directed memory-like NK cell responses during secondary infection in vaccinated people." (PMID 30873151, 2019). "Whole CD4+ T cells were pooled from the infection site, the pleural cavity (PleC), and the LN within the thoracic cavity (tLN) that drain the PleC, as Th2 cell-intrinsic hypo-responsiveness occurs at both locations and cell numbers were limiting." (PMID 31815932, 2019). "The frequency and number of CD4+Foxp3+ cells expressing T-bet also increased during infection albeit to lower levels than effector CD4+ T cells expressing T-bet." (PMID 30915078, 2019). "As revealed by the dual-color flow cytometry analysis, the change in the percentage of CD4+ T cells in the vaginal draining lymph nodes between pre-infection and post-infection varied among groups." (PMID 30621597, 2019). "We found that preexposure of CECs or RBCs to HIV-1 (R5-tropic) resulted in carriage of the virus and trans-infection of CD4+ T cells when analyzed 4 days post-coculture." (PMID 31772057, 2019). "A similar increase in the CD4+ compared to CD8+ T cells was observed in other mouse models of infection in which AOM was induced by NTHi." (PMID 31548315, 2019). "LmOVA infection induced a strong formation of LLO189-201–specific CD4+ and OVA257-264–specific CD8+ T cells in spleens of mice." (PMID 29742141, 2018).
infection (continued). "This is in agreement with previous studies reporting an increase in the proportion of CD4+ T cells in the blood of TB patients compared to uninfected controls and a much higher number of CD4+ T cells at the site of infection." (PMID 30409122, 2018). "While the formation of the infectious synapse does not rely on CD4/gp120 interaction, this interaction is still required for efficient productive infection of CD4+ T cells following formation of cell-to-cell conjugates with DCs carrying HIV-1." (PMID 29515578, 2018). "Our data further revealed that productive infection of female genital epithelial cells resulted in release of pseudotyped HIV-1, which led to efficient HIV-1 transmission to susceptible CD4-positive target cells." (PMID 29624497, 2018). "Our present study highlights the importance of neddylation in proper CD4+ T cell responses to P. yoelii 17XNL infection." (PMID 30462731, 2018). "HIV targets the key cells of the immune system, the CD4+ T cells which are required to fight infection." (PMID 30344234, 2018). "The F3 domain was also responsible for the CD4+ T cell-mediated protection against mice infection by L. (L.)amazonensis." (PMID 29867949, 2018). "Our results also suggest that for ZIKV, compared to DENV, CD4+ T cells are more relevant to the control of infection." (PMID 30087337, 2018). "Pre-formed, neutralizing antibodies induced by prior vaccination prevent infection by live virus in vivo, shifting antigen presentation toward the exogenous antigen presenting pathway and thereby favoring CD4 responses while dampening CD8 responses." (PMID 29666412, 2018). "CD32high CD4 T cells had higher levels of HLA-DR and HIV co-receptor expression than other subsets, compatible with their being more susceptible to infection." (PMID 29780387, 2018). "Most importantly, SIMV blocked the ability of MΦ to significantly enhance trans infection of CD4+ T cells compared to cis infection." (PMID 29643243, 2018). "At 3 days post infection (dpi), we found an increased recruitment of macrophages, cluster of differentiation (CD)8α+ and CD4+ T lymphocytes, and an up-regulation of interferon (IFN)-γ mRNA in the respiratory tract of the chickens." (PMID 30445707, 2018). "In contrast, our model examined infection after a longer period post-initial infection (day 28), and it seems that the contribution of ILC2s becomes higher than that of CD4+ T cells when the second infection occurs later." (PMID 30283458, 2018). "Organisms proliferate in the lungs for a short period until a threshold level is reached and a CD4+ T cell-dependent adaptive immune response clears the infection." (PMID 30283457, 2018). "To determine if p19Arf repression by Ezh2 HMT contributes to the early TFH lineage specification, we analyzed the behavior of adoptively transferred, CTV-labeled Ezh2–/–Arf–/– Smarta CD4+ T cells in response to LCMV-Arm infection." (PMID 30575739, 2018). "In this model we were not able to discriminate virtual patients between those with a stronger or weaker immune system at the time of the infection and this explains the difference in the initial number of CD4+ cells." (PMID 30021018, 2018). "We therefore conclude that the HIV-1 accessory proteins are not required to mediate the upregulation of HK1, and by extension, glycolysis, upon infection of CD4+ T cells." (PMID 29518929, 2018). "It has been shown that lymphoid aggregates, which contained CD4 T cells, are formed in the genital tract of mice during infection with C. trachomatis." (PMID 30147701, 2018). "Among patients diagnosed with chronic HIV infection, 62% (N = 76) had an advanced disease (CD4 <200 cells/mm3) and 57% (N = 70) a newly diagnosed infection." (PMID 30362663, 2018). "In this study, using a mouse model of influenza A infection and an unbiased method of epitope identification, the viral epitope-specific CD4 T cells elicited after infection were identified and quantified." (PMID 29681900, 2018).
infection (continued). "We therefore sought to assess the full range of glucose transporters expressed by human CD4+ T cells and their modulation upon infection with HIV-1." (PMID 29518929, 2018). "The investigation of glycolytic enzymes demonstrated activation-dependent expression of hexokinases HK1 and HK2 in human CD4+ T cells, and a highly significant increase in cellular hexokinase enzyme activity in response to infection with HIV-1." (PMID 29518929, 2018). "Meanwhile, the proportion of Treg cells in the total splenic CD4+T cell population showed a continuous increase after infection." (PMID 29577333, 2018). "The full repertoire of GLUT proteins expressed by human CD4+ T cells upon activation and infection with HIV-1 has, to date, remained unexplored." (PMID 29518929, 2018). "Vaccination with WC-rBS also results in CD4 T-cell responses skewed toward a Treg (tolerance inducing) response rather than the TH1 and TH17 response associated with natural infection." (PMID 30184117, 2018). "The phenotype of the transferred CD4 T cells also was characterized in mice euthanized at day 7 after infection." (PMID 30006528, 2018). "Intriguingly, among patients analyzed in DENV group, the lowest values for all chemokine receptors expression on CD4+ T cells were observed for patient 2, in which cells were obtained 22 days post infection, even though viral genome was still detected." (PMID 29282904, 2018). "Intriguingly, CD4+ T-cell responses to Gag and Pol were detected at several time points in the year pre-infection, and confirmed in a repeat assay." (PMID 29370775, 2018). "Our results showed that PAS-5 significantly promoted the production of CD4+ T cells after L3 infection, while Gal-1 had little effect on this cell type, compared with the control group." (PMID 29843794, 2018). "As an example, CD4+ T cells play a major role in the clearance of parasite Plasmodium chabaudi chabaudi blood stage infection." (PMID 29892278, 2018). "HIV-1 also uses DC-SIGN and L-SIGN expressed by antigen presenting cells for its delivery to target cells such as CD4+ lymphocytes by trans-infection." (PMID 30086792, 2018). "Results showed that indeed CD200R expression is correlated with the acquisition of LAG3 and CD49b markers on CD4+ T cells in LdWT infection compared to LdCen−/− immunization (p = 0.0006 between LdWT and LdCen−/−)." (PMID 29915577, 2018). "Analysis of the immune response during infection revealed that T cells from TACC1 mice exhibited reduced frequencies of IFN-γ+ CD4 T cells indicating the importance of T cell-intrinsic FAS for mounting Th1 responses." (PMID 29675017, 2018). "Compared with the HIV-1-infected group, CD4+ T-cell activation in the SIVcpz-infected group was significantly lower (p < 0.001) at all time points post-infection." (PMID 29615603, 2018). "IFN-α4 and IFN-β1 are necessary for the clearance of virus, and IFN-γ is important to regulate the cytokine production and CD4+ T cell activation during infection." (PMID 29896425, 2018). "Curiously, endocytosis of HIV-1 particles has been demonstrated to result in productive infection in CD4+ T lymphocytes." (PMID 30364166, 2018). "We found that a very diverse specificity of CD4 T cells is primed by infection, including epitopes from hemagglutinin, neuraminidase, matrix protein, nucleoprotein, and non-structural protein-1." (PMID 29681900, 2018). "Resting memory CD4+ T-cells, which are less permissive to infection than activated CD4+ T-cells, display increased levels of five cellular miRNAs that target and inhibit several HIV-1 mRNAs." (PMID 30126238, 2018). "To remove any potential contribution of CD4+ T cells in the phenotype observed, we treated both Hic1fl/fl and Hic1Rorc mice with a depleting antibody against CD4 prior to infection with C. rodentium." (PMID 29470558, 2018).
infection (continued). "By day 8 p.i. greater than 90% of the NK1.1+CD4+ T cells expressed ICOS, and the frequency of ICOS+ cells remained significantly higher amongst the NK1.1+CD4+ T cells through the peak of infection." (PMID 30374346, 2018). "According to clinical evidence, it appears that spontaneous clearance of clinical infection correlates with at least partial protection against C. trachomatis through the production of INF-γ-secreting cells such as CD4+ Th1 cells." (PMID 30038624, 2018). "Analysis of the relative contribution of CD8+ vs. CD4+ T cells to express IFNγ following v2.2-1 infection surprisingly revealed that CD4+ T cell express higher levels of IFNγ mRNA at the population levels than CD8+ T cells." (PMID 30619363, 2018). "CCR4−/− mice exhibited a lower frequency of CD4+Foxp3+ cells at 15, 30, and 70 days of infection than their wild-type counterparts." (PMID 30584243, 2018). "Other factors previously shown to be associated with neutralization breadth, such as high viral load and low CD4 count, in this and other cohorts, were also seen early in infection." (PMID 29630668, 2018). "Pathogen-specific CD4 TRM cells produced IFN-γ in response to secondary infection and rapidly recruited other memory cells from the circulation; however, recruitment and activation of inflammatory monocytes was required for optimal protection." (PMID 30147701, 2018). "Here, we provided evidence to suggest that the CD4+ T cell response to a model retroviral antigen, presented during natural infection, is heavily skewed toward Tfh differentiation." (PMID 29951052, 2018). "At 3 days after intraperitoneal VACV infection, the frequency of IFNγ+CD4+ T-cells in mesenteric lymph nodes and peritoneal exudate was lower in Lmna−/− mice than in WT mice." (PMID 29311549, 2018). "In search for the underlying mechanisms, we demonstrate reduced Bcl-6 accompanied by accumulated FoxO1 proteins in CD4+ T cells of Uba3ΔT mice, either under the circumstance of P. yoelii 17XNL infection or the iTfh cultures." (PMID 30462731, 2018). "In the skin, CD8+ TRM can be generated following an infection and CD4+ IL-17-producing TRM cells were identified in the skin of the mice when they were infected by C. albicans (part of skin mycobiome)." (PMID 29900173, 2018). "Following listeria-infection of mice, the majority of listeria-specific CD4+ and CD8+ T cells were CD39+ and CD73—." (PMID 29742141, 2018). "In memory phase, commensal-specific CD4+ T cells behave like pathogen-specific CD4+ T cells, persisting after clearance of infection but declining in numbers over time." (PMID 30524431, 2018). "We again noted a blunting of FIV viral loads in blood and peripheral tissues and a dampening of CD4 depletion when PLV infection preceded FIV challenge." (PMID 29677149, 2018). "Independent-T test assuming unequal variances was used to compare differences between age and gender whilst the Mann–Whitney U test checked for significant differences in the sum ranks of the CD4 count and duration of infection by gender." (PMID 29941015, 2018). "In fact, the Leishmania lysate stimulus also increased the frequencies of CD4+-secreting T cells, more on day 15 than on day 28 after infection." (PMID 29867949, 2018). "CD4+T cell depletion was confirmed by flow cytometry analyses of blood on all of the mice (n = 12) on day 4 post infection and it was determined that less than 1% of the CD4+T cells remained in mice from the depleted group." (PMID 30212537, 2018). "The proportion of variation in the number of challenges to infection explained by the percentage of CD4+ T cells that expressed CD69 was estimated to be 0.36 as determined by a discrete-time Cox model with percent CD4+ T cells specified quadratically." (PMID 29359183, 2018). "Infection in resting CD4+ T cells stimulated by endothelial cells (HUVEC) takes place much slower than in activated T cells." (PMID 30285810, 2018).
infection (continued). "Subsequently, nocodazole was either removed after 16 h, allowing CD4+ T cells to exit mitosis/enter G1 phase (“inf”), or nocodazole treatment was continued until 24 h post-infection (“inf + N”) to keep cells in mitosis." (PMID 29884836, 2018). "In Il27ra−/− mice, however, the number of virus-specific CD4+ T cells was actually heightened at day 9 after LCMV Cl13 infection, though it returned to numbers similar to those of WT mice at day 30 p.i.." (PMID 29593047, 2018). "Adoptive transfer of parenchymal TRM cells into susceptible T cell-deficient hosts showed preferential migration back to the lung and superior control of infection compared with the intravascular CD4 T cells." (PMID 30147701, 2018). "This observed phenotype of Plasmodium-responsive effector memory and memory CD4 T cells was further evidenced by measurements at 15 days of infection." (PMID 30006528, 2018). "As expected, the absolute number of ILCs and CD4+ T cells expressing type 2 cytokines were increased in the lungs following infection, with approximately 10-fold greater numbers of CD4+ T cells than ILCs." (PMID 30500858, 2018). "We identified specific lymphocyte subsets that are pivotal for efficient containment of the infection and showed that this process requires cooperation between CD4 and CD8 T cells." (PMID 30153311, 2018). "Cross-validation and simulation analyses indicate that the models developed provide more accurate information regarding the timing of infection than does CD4 count-based estimation." (PMID 29945571, 2018). "From 4–22 weeks post infection CD4+ T cells isolated from the lung were assessed for ex vivo production of TH1 cytokines by intracellular flow cytometry." (PMID 29795025, 2018). "In mice, LCMV infection redirects CD4+ T cell development away from the Th1 cell responses induced during an acute infection toward TFH cells." (PMID 29535724, 2018). "When we remove the spatial aspect, we effectively assume that tissue damage and CD4+ T cell counts are uniform across the simulation region, removing possible hot spots for infection." (PMID 29698393, 2018). "Recent studies on lung infection with N. brasiliensis revealed that a Th2-type polarized pulmonary CD4 T cell population established during infection and can drive effective local adaptive immunity to reinfection with the same parasite." (PMID 30147701, 2018). "Of note, the CD4(1+2) BiTE promoted infection of CD8+/CD4- T cells in vitro, possibly due to effects on gp120 conformation, whereas the other constructs did not." (PMID 30564246, 2018). "Active infection of primary CD4+ T lymphocytes with both HIV-1 and HTLV-1 was confirmed by quantifying de novo viral DNA in the cells and virus release into culture supernatants." (PMID 29624497, 2018). "Recent work in CD4 +T cells has similarly demonstrated enhanced infection and/or viral production in T cells on stimulation of TLR2." (PMID 30520725, 2018). "Flow cytometric analyses revealed declines in the absolute numbers of CD4+ T cells during the first year after infection in all four groups." (PMID 29636452, 2018). "Second, to investigate the in vivo infectivity of EcoHIV from CD4+ reservoirs, cells purified from male 129X1 mice 6 weeks after infection were transferred to athymic (nude) females of the same breed." (PMID 29879225, 2018). "At day 6 post infection, depletion of CD4 T cells resulted in significantly reduced frequencies of IFN-γ+ and TNF-α+ ILC1s." (PMID 29623077, 2018). "Follicular helper CD4 T cells (TFH) have been reported as a major cell compartment contributing to viral persistence, consequent to their susceptibility to infection and ability to release replication-competent new virions." (PMID 29967602, 2018). "HIV-1 is known to productively infect activated CD4+ T cells, but resting cells are refractory to infection." (PMID 29518929, 2018).